PVR (PVR cell adhesion molecule)
Diseases named in the same sentence as PVR in open-access papers (continued):
Sharing a sentence is not in itself a finding about the gene and the disease.
Alzheimer disease (2 papers, 2021). A progressive, neurodegenerative disease characterized by loss of function and death of nerve cells in several areas of the brain leading to loss of cognitive function such as memory and language. "We have shown that a decrease in expression of PVR is associated with Alzheimer’s disease in LPS-induced monocytes (24 h) and this result replicated using independent summary statistics (Marioni)." (PMID 33959712, 2021). "LACTB2 and PLIN2 had novel significant associations with Alzheimer’s disease and BIN1, PTK2B, SPI1, MS4A4A, MS4A6E, APOE and PVR are in known Alzheimer’s disease risk loci from GWAS." (PMID 33959712, 2021). "We have shown that genetically predicted PVR expression is correlated with the number of APOE e4 alleles, and that the TWAS association with Alzheimer’s disease risk may therefore be due to APOE effects." (PMID 33959712, 2021). "We have shown an association between changes in gene expression in naïve and induced CD14+ monocytes and Alzheimer’s disease in seven genes in known Alzheimer’s disease loci, three of which (PVR, PTK2B and MS4A6E) replicated in TWAS using independent summary statistics." (PMID 33959712, 2021). "The best eQTL (expression quantitative trait locus) SNP in Alzheimer’s disease-relevant tissues, rs10426401 is in a regulatory region in the first intron of PVR which could affect several transcription-factor binding sites." (PMID 33959712, 2021). "The best eQTL SNP in Alzheimer’s disease-relevant tissues, rs10426401 is in a regulatory region in the first intron of PVR and could affect several transcription-factor binding sites." (PMID 33959712, 2021).
bladder urothelial carcinoma (2 papers, 2021 to 2023). "Noticeably, these ligands, in particular PVR, are potential prognostic markers in AML, MM, hepatocellular carcinoma, and bladder urothelial carcinoma (BLCA)." (PMID 37359555, 2023).
cutaneous melanoma (2 papers, 2012 to 2022). A primary melanoma arising from atypical melanocytes in the skin. "As in cutaneous melanoma, the anti-MAA clonotypes formed frequent inhibitory interactions with tumor cells via PVR – TIGIT/CD96 and with immune cells via Galectin 9 – TIM3." (PMID 36220826, 2022).
gynecologic cancers (2 papers, 2021 to 2024). "It has also been shown that patients with lung, gastrointestinal, breast, and gynecological cancers have higher levels of soluble PVR in their serum than healthy donors." (PMID 39156900, 2024). "Specifically, soluble PVR is a valuable biomarker for cancer development, where higher soluble PVR levels are detected in lung, gastrointestinal, breast, and gynecologic cancers compared to healthy donors, being even higher at advanced stages of the disease." (PMID 34447383, 2021).
rhabdomyosarcoma (2 papers, 2013 to 2021). A rare aggressive malignant mesenchymal neoplasm arising from skeletal muscle. "Virus isolation is sensitive but can be lengthy (minimum of 10 days), and requires maintaining two cell lines, the L20B (mouse L cells expressing the human PV receptor [PVR; CD155]) and human rhabdomyosarcoma (RD) cell lines." (PMID 34727100, 2021).
serous ovarian cancer (2 papers, 2021 to 2022). "Three auto-antibodies, against NUDT11, PVR, and TRIM39, were consistently selective for serous ovarian cancer with individual sensitivities ranging from 14.7% to 32.4% at 96% specificity." (PMID 33672007, 2021).
type 2 diabetes (2 papers, 2021 to 2023). "Metformin (P = 8.30 × 10−12), which affects 11 of the 34 PVR genes, is the most used drug for type 2 diabetics and was found in a list of the top 100 filtered compounds." (PMID 37191619, 2023).
cleft lip and palate (1 paper, 2009). "Here, we carried out mutation screening of the PVR and PVRL2 genes, which are both located at an OFC linkage region at 19q13 (OFC3) and are closely related to PVRL1, which has been associated with both syndromic and non-syndromic cleft lip and palate (nsCLP)." (PMID 21637507, 2009).
cutaneous T-cell lymphoma (1 paper, 2024). "In cutaneous T-cell lymphoma (CTCL), PVR is highly expressed in tumor cells." (PMID 39156900, 2024).
emphysema (1 paper, 2026). "Alveolar macrophages exhibited extensive dysregulation of immune checkpoint ligand; notably, PVR (CD155) expression was reduced in severe emphysema, while experimental PVR overexpression suppressed pro-inflammatory gene expression in both alveolar and interstitial macrophages." (PMID 41684927, 2026).
kidney stones (1 paper, 2024). "Accordingly, depletion of Crk, mbc, and hep in the background of PVR activation flies rescued the bloating phenotype and abnormal uric acid levels, which also partially inhibited kidney stones and improved the survival of these flies." (PMID 38336808, 2024).
mantle cell lymphoma (1 paper, 2023). Mantle cell lymphoma is a rare form of malignant non-Hodgkin lymphoma affecting B lymphocytes in the lymph nodes in a region called the ``mantle zone''. "Acquired TIGIT expression in TCs with mantle cell lymphoma relapse enhances the interaction of TIGIT+ TCs with monocyte CD155/PVR 44, suggesting that a rational strategy could be considered for targeting TIGIT to enhance the anti-tumor immunotherapy efficacy." (PMID 37649613, 2023).
metastasis (1 paper, 2016). The spread or migration of cancer cells from one part of the body (where they first appeared) to another. "The methylation level of the CGI located on the PVR gene body in SCC was correlated to regional lymph node metastasis (P = 0.013, Mann-Whitney U test)." (PMID 27788211, 2016).
monoclonal gammopathy of undetermined significance (1 paper, 2017). "Interestingly, in MMECs the surface density of PVR was significantly higher than that detected in endothelium from patients with MM in complete remission or with monoclonal gammopathy of undetermined significance (MGUS)." (PMID 28456791, 2017).
Obesity (1 paper, 2020). Accumulation of substantial excess body fat. "Only oenocyte-specific loss of PvR signaling phenocopies the obesity phenotype caused by muscle-specific loss of Pvf1, indicating that muscle-Pvf1 primarily signals to the oenocytes to regulate systemic lipid content." (PMID 33107824, 2020). "Similarly, impairing PvR signaling in the oenocyte by expressing an RNAi against pvr (oenots>pvr-i) also leads to obesity." (PMID 33107824, 2020). "Since our data shows PvR and PvR-signaling to be enriched in the oenocytes, we asked whether PvR signaling in the oenocyte is necessary for protecting the adult flies against obesity." (PMID 33107824, 2020). "We further investigated whether TORC1 functions downstream of PvR signaling to regulate lipid accumulation by testing whether co-expression of a constitutively active form of rheb (rhebAV4) can rescue the obesity phenotype observed in oenots>pvrDN flies." (PMID 33107824, 2020). "Single nuclei-RNA-sequencing reveals that oenocyte-specific PvR signaling protects against obesity." (PMID 33107824, 2020). "Altogether, we demonstrate that in Drosophila, muscle-derived Pvf1 signals through PvR in the oenocyte to activate TOR, which in turn protects the animal against obesity." (PMID 33107824, 2020). "Surprisingly, over-expressing pvrDN in the adult adipose tissue and muscle did not lead to an obesity phenotype indicating that Pvf/PvR signaling is primarily required in the oenocytes to regulate lipid abundance." (PMID 33107824, 2020).
ovarian tumor (1 paper, 2025). "Using a Kras, Myc, FAK (KMF) syngeneic ovarian tumor mouse model, decreased tumor burden, suppressed ascites KMF-associated CD155/Polio Virus Receptor (PVR) levels, and increased peritoneal TILs were observed with blocked FAK activity." (PMID 40475770, 2025).
paraneoplastic renal syndrome (1 paper, 2024). Paraneoplastic syndrome that involves the renal system. "Specifically, we find that Pvf1, a PDGF/VEGF signaling ligand, secreted by gut tumors activates the PvR/JNK/Jra signaling pathway in the principal cells of the kidney, leading to mis-expression of renal genes and paraneoplastic renal syndrome-like phenotypes." (PMID 38336808, 2024).
plasmacytoma (1 paper, 2022). Plasmacytoma is a localized mass of neoplastic monoclonal plasma cells that represents approximately 5% of all plasma cell neoplasms. "PVR expression was significantly associated with the Revised-International Staging System stage, presence of extramedullary plasmacytoma and bone lesion, percentage of bone marrow plasma cells (BMPCs), and β2-microglobulin levels, suggesting a possible role in advanced stages and metastasis." (PMID 35625835, 2022).
psoriasis (1 paper, 2023). An autoimmune condition characterized by red, well-delineated plaques with silvery scales that are usually on the extensor surfaces and scalp. "Collectively, our results suggest that the minimal IgV domain of PVR is sufficient to dampen immune responses in-vitro and attenuate symptoms of psoriasis in-vivo." (PMID 36944702, 2023). "Here, we developed a minimal murine PVR-Fc fusion construct, consisting of only the IgV domain of PVR (vdPVR-Fc), and assessed its ability to dampen inflammatory responses in a murine model of psoriasis." (PMID 36944702, 2023). "PVR-Fc has not been tested in the context of an in-vivo mouse model of psoriasis." (PMID 36944702, 2023).
rubella (1 paper, 2014). A viral infection caused by the rubella virus. "Although relatively rare, the heterozygous genotype of these PVR SNPs (no homozygous minor allele genotype was observed) was consistently associated with a significant decrease (> 2-fold) in neutralizing antibody titers after rubella vaccination in both cohorts." (PMID 24945853, 2014). "Therefore, it is likely that DC-SIGN, PVR, PVRL2 or other attachment factors and/or cellular viral receptors and pathway-related genes are involved in the genetic control of rubella vaccine-induced immune response heterogeneity after vaccination." (PMID 24945853, 2014).
yolk sac tumor (1 paper, 2025). A non-seminomatous malignant germ cell tumor composed of primitive germ cells. "In contrast, yolk sac tumors displayed an immunosuppressive environment with high CD24 and PVR expression, indicative of unique immune evasion mechanisms." (PMID 40621458, 2025).
ZIKV infection (1 paper, 2022). "Notably, we detected the downregulation of two genes, Leukemia Inhibitory Factor (LIF) and Poliovirus Receptor (PVR), related to other viruses yet not currently linked to ZIKV infection." (PMID 35304593, 2022).
tumor (606 papers, 2004 to 2026). "For patients with high-risk tumours, a high expression of PVR also led to a reduced event-free and overall survival whereas a high expression of PVRL2 led only to a lower event-free survival probability." (PMID 40317320, 2025). "Spatial transcriptomics also demonstrated a direct association between VPS25 and PVR expression in tumor regions." (PMID 40149859, 2025). "TIGIT binds with high affinity to the poliovirus receptor (PVR) and is associated with impaired T cell and NK cell function, as well as impaired anti-tumor immunity." (PMID 38451273, 2024). "During this 24-hr period, the probability of ERK activation in NK cells upon encountering the tumor cells was decreased from 68% to 8%, which correlated with the loss of the activating ligand CD155/PVR/Necl5 from the tumor cell surface." (PMID 35113018, 2022). "High PVR expression on tumor cells was also associated with TILs (assessed with Salgado’s criteria (p=0.011), CD3 (p=0.002) or CD8 immunostaining (p=0.024)), and PD-L1+ tumor and stromal cells (p=0.003 and p<0.001, respectively)." (PMID 36544779, 2022). "Its main ligand is PVR, which is usually overexpressed on tumor cells and tumor-associated myeloid cells, although other proteins, such as CD112 and CD113, also interact with this receptor." (PMID 35954196, 2022). "Accumulating evidence suggests that PVR overexpression induces the immune escape of tumor cells and is associated with a poor prognosis and enhanced tumor progression." (PMID 36377656, 2022). "LSM12, LSM14A, and LSM14B overexpression is also associated with higher tumor-related immune checkpoints (e.g., PD-L1, B7-H3, and PVR) expression and increased therapeutic insensitivity to immune checkpoint blockade (ICB)." (PMID 35646684, 2022). "In consistent with TCGA cohort, PVR expression was also significantly correlated to tumor purity, as it was positively associated with stromal, immune and ESTIMATE scores." (PMID 34150627, 2021). "PVR expressed by tumor and tumor-associated myeloid cells can interact with three lymphocyte-expressed receptors to modulate their functions." (PMID 34150627, 2021). "Of note, up-regulation of PVR has been reported on a variety of different tumor cells, which leads to tumor invasion and progression and is known to be associated with worse outcome." (PMID 34102454, 2021). "CD155 (PVR/Necl5/Tage4) is a member of the nectin-like adhesion molecule family, which is highly upregulated on tumor cells of many cancer types and is associated with poor patient prognosis." (PMID 33994860, 2021). "TIGIT and TACTILE/CD96 are inhibitory co-receptors expressed by both T and NK cells, and are linked to the CD112 (Nectin-2) and CD155 (PVR) expressed by APCs, infected cells and tumor cells." (PMID 34359767, 2021). "The vector binds to CD155 (poliovirus receptor, PVR or NECL5), internalizes and eventually causes tumor cell lysis." (PMID 33322507, 2020). "PVR is frequently overexpressed in human malignancies, and is associated with tumor progression, poor prognosis and immune escape." (PMID 33584669, 2020). "In particular, recent therapeutic approaches aim to target PVR, which is expressed by several tumor histotypes and by tumor-associated endothelium." (PMID 31447858, 2019). "We have also provided evidence that the SUMO pathway regulates PVR surface expression in tumors other than MM, supporting a more general role for this modification in regulating tumor cell susceptibility to NK cell-mediated cytotoxicity." (PMID 28874810, 2017). "PVR (Poliovirus Receptor) and B7-H3 are promising targets, since they are expressed by most high-risk NB, are upregulated in tumor vasculature and are essential for tumor survival/invasiveness." (PMID 24575100, 2014). "Elevated PVR expression may be linked to immune evasion mechanisms and tumor aggressiveness, suggesting its utility in monitoring disease progression or therapeutic response." (PMID 40369504, 2025).
tumor (continued). "It is well known that PVR is associated with the tumor immune microenvironment." (PMID 39120585, 2024). "The high expression of PVR and Nectin-2 in tumor cells could make them strongly susceptible to DNAM-1 chimeric receptor-engineered NK cell-mediated recognition and killing." (PMID 37359555, 2023). "Thus, tumor exposure resulted in close to 80% loss in the IFNγ generation capacity with about 30% of this loss being dependent on TIGIT/PVR engagement." (PMID 37345049, 2023). "Besides lymph node status, only high expression of TIGIT, PVR and PD-L1 on tumor cells remained independently associated with better RFS in multivariate analysis." (PMID 36544779, 2022). "In addition, the low-dose radiation component reduced TIGIT receptor (PVR) expression by tumor-associated macrophages and dendritic cells in secondary tumors." (PMID 35008385, 2022). "The increased PVR expression level has been associated with poor clinicopathologic features including lymph node metastasis, a reduction in tumor-infiltrating lymphocytes, tumor histological grade, and poor prognosis in retrospective studies among various solid cancer types." (PMID 34150627, 2021). "PVR expression is associated with the invasion, migration, and proliferation of tumor cells." (PMID 33879814, 2021). "Furthermore, PVR expression is commonly upregulated in several types of cancer and tumor-associated myeloid cells." (PMID 33670993, 2021). "Moreover, DNAM-1-deficient mice show an impaired clearance of PVR-expressing tumor cells and develop more tumors in response to chemical carcinogens." (PMID 24432022, 2014). "Moreover, PVR overexpression is associated with poor prognosis and enhanced tumor progression." (PMID 35625835, 2022). "Thus, in NB the presence of PVR, originally described as an adhesion molecule, could become critical in rendering tumor cells susceptible to NK-mediated killing." (PMID 24575100, 2014). "PVR is upregulated in tumor development, enhancing tumor proliferation, migration, and invasiveness." (PMID 40369504, 2025). "Tumor cells coexpressing PVR and PVRL2 are common in various malignancies, particularly endometrial tumors." (PMID 40567374, 2025). "Monoclonal antibodies that have been successfully developed block the interaction between KIR2DL5 and PVR in multiple humanized tumor models, providing novel therapeutic strategies for cancer immunotherapy." (PMID 40463500, 2025). "High expression of PVR and MAG genes in U87-MG cells is associated with poor prognosis due to their role as cell adhesion molecules promoting tumor growth and metastasis." (PMID 40739397, 2025). "Similar to NKG2A, tumor cell‐expressed PVR binds TIGIT on NK cells, resulting in suppression of antitumor immunity." (PMID 40959206, 2025). "DNAM-1 (CD226) is a critical activating receptor on the surface of NK cells that mediates their activation by recognizing ligands such as Nectin-2 (CD112) and PVR (CD155), which are expressed on the surface of tumor cells." (PMID 40463500, 2025). "DNAM-1 binds two main ligands also expressed on the surface of tumor cells or virus-infected cells, CD155 (poliovirus receptor, PVR) and CD112 (nectin-2)." (PMID 40211394, 2025). "Nonetheless, BCG treatment is associated with diverse immune-escape mechanisms, including the loss of MHC-I or the up-regulation of PD-L1 and poliovirus receptor (PVR or CD155) in tumor cells." (PMID 39857739, 2025). "This strategy eliminated GSH and disrupted the TIGIT/PVR signaling axis, thereby strengthening the anti-tumor immune response and inhibiting tumor growth." (PMID 40403492, 2025). "The moderate and significant correlation of M protein with PVR gene expression (rs = 0.432, p = 0.002) and serum levels (r = 0.316, p = 0.018) further links PVR to tumor burden and disease activity." (PMID 40369504, 2025). "Research has demonstrated that when PVR is depleted from the tumor cell surface, the KIR2DL5-mediated inhibition of NK cell cytotoxicity is abrogated." (PMID 40463500, 2025).